RNU4-81P (RNA, U4 small nuclear 81, pseudogene)
Gene: Small nuclear RNA gene on chromosome X (70,450,879 to 70,451,022, forward strand). Ensembl gene ENSG00000200431.
Homologues: Orthologues: chimpanzee U4 (100% identical), macaque U4 (93% identical). Paralogues in human: RNU4-49P (80% identical), RNU4-10P (77% identical), RNU4-36P (75% identical), RNU4-32P (74% identical), RNU4-50P (72% identical), RNU4-17P (72% identical), RNU4-90P (70% identical), RNU4-51P (69% identical), RNU4-46P (69% identical), RNU4-83P (69% identical), RNU4-15P (68% identical), RNU4-28P (65% identical), and 81 more.